INS (insulin)
Diseases named in the same sentence as INS in open-access papers (continued):
Sharing a sentence is not in itself a finding about the gene and the disease.
metabolic syndrome (continued). "This is summarized by a significant decrease in the Met-S score based on WC, reflecting lower severity of the metabolic syndrome, as well as a significant decrease in the TyG-WHtR, reflecting improvement in insulin sensitivity (both p < 0.001)." (PMID 41002980, 2025). "By exploring shared metabolic pathways, such as insulin sensitivity, lipid metabolism, inflammation, and body composition, this review contributes a novel, integrative perspective to the management of metabolic syndrome." (PMID 40362807, 2025). "This carbonylation impairs mitochondrial respiration, increases superoxide production, and disrupts insulin signaling pathways, contributing to metabolic dysregulation and the progression of metabolic syndrome." (PMID 41235339, 2025). "Systemically, OS perturbs insulin signaling and contributes to insulin resistance, dyslipidemia, and metabolic syndrome." (PMID 40563291, 2025). "Chronic low-grade systemic inflammation, induced by this dietary imbalance, disrupts insulin signaling pathways, promoting insulin resistance, dyslipidemia, and hepatic lipid accumulation, all of which contribute to liver damage." (PMID 40227294, 2025). "This review examines the potential contributions of the oral microbiome in the pathogenesis of metabolic syndrome, emphasizing its impact on insulin resistance, systemic inflammation and adipokine secretion." (PMID 40862144, 2025). "This condition is characterized by impaired insulin action, leading to metabolic disturbances such as dyslipidemia, which can negatively influence the prognosis of patients with acute illnesses requiring intensive care, including those on VA-ECMO support." (PMID 40475963, 2025). "IR is a core indicator of metabolic syndrome, which refers to the body’s reduced sensitivity to insulin, which triggers a series of metabolic abnormalities." (PMID 40275575, 2025). "In patients with metabolic syndrome, insulin‐stimulated renal GU increases concomitantly with a small decrease in body adiposity, independently of changes in whole‐body glucose disposal." (PMID 40692323, 2025). "Mechanistically, alterations in these proteins can indicate changes in insulin signaling, glucose metabolism, and metabolic syndrome." (PMID 39941463, 2025). "Compensatory activation of sterol regulatory element-binding protein 1c (SREBP-1c) sustains de novo lipogenesis despite insulin resistance, while impaired adipocyte insulin response exacerbates dyslipidemia through reduced FFA uptake and TG synthesis." (PMID 40699849, 2025). "Among participants with metabolic syndrome and healthy controls, serum FFA concentration prior to drug pretreatment was negatively associated with insulin‐mediated, endothelium‐dependent vasodilation." (PMID 39888728, 2025). "Recently, it was reported that liver-specific, genetically engineered mice showed impaired liver insulin activity, increased dyslipidemia, and elevated HGP." (PMID 40141412, 2025). "Fecal microbiota transplantation (FMT), the transfer of stool from a healthy donor, is being tested in clinical trials as an adjunctive therapy to improve insulin sensitivity in metabolic syndrome and increase responsiveness to cancer immunotherapies." (PMID 41374093, 2025). "Optimal Zn levels confer significant health benefits, such as enhanced antioxidant capacity and improved insulin sensitivity, while excessive intake poses risks, including oxidative stress, dyslipidemia, and systemic inflammation." (PMID 41459237, 2025). "The non-alcoholic fatty liver disease (NAFLD) Liver Fat Score, which incorporates the presence of metabolic syndrome or T2DM, serum AST, the AST/ALT ratio, and fasting insulin levels, demonstrates high diagnostic accuracy." (PMID 41104308, 2025). "Predictors of metabolic syndrome were the need for insulin therapy for glycaemic control of GDM, maternal BMI at the postpartum visit, and absence of breastfeeding." (PMID 39940248, 2025).
metabolic syndrome (continued). "Glucose intolerance and decreased insulin sensitivity are relieved, indicating that dyslipidemia and glucose metabolism disorders were improved in LNP mice." (PMID 40562101, 2025). "Among these, the blue and green clusters encompass terms such as “glucose homeostasis,” “insulin secretion,” and “metabolic syndrome,” which collectively embody core concepts related to the regulation of basal metabolic states in T2DM." (PMID 40941440, 2025). "An HFD induces dyslipidemia through multiple interrelated mechanisms, including the enhanced absorption of exogenous lipids, the stimulation of hepatic lipid synthesis, insulin resistance, reduced activity of lipolytic enzymes, and chronic inflammation." (PMID 41011571, 2025). "L. reuteri ATCC (strain PTA 4659) can also reduce serum insulin levels in adult mice with metabolic syndrome (Apoe−/− mice fed a high-fat diet) (Fåk and Bäckhed 2012)." (PMID 39520540, 2025). "Apparently, a combination of cinnamon extract and insulin induces a synergistic effect on the regulation of dyslipidemia and the insulin signaling pathway." (PMID 40722869, 2025). "Exercise is one of the most effective lifestyle interventions for enhancing insulin sensitivity and improving glucose metabolism, both of which are critical for individuals with metabolic syndrome." (PMID 40362807, 2025). "The proposed cut-off for hyperinsulinemia is fasting insulin >85 pmol/L (12.2 mIU/L), which is adequate to mark the condition of metabolic syndrome." (PMID 40735043, 2025). "Research findings reveal that galangin can effectively lower arterial pressure, blood glucose, insulin, and cholesterol levels in rats with metabolic syndrome." (PMID 40333577, 2025). "Metabolic syndrome and the dysregulation of insulin signaling play critical roles in glucolipotoxicity and the proinflammatory response, which causes oxidative stress." (PMID 40309844, 2025). "Waist circumference is a critical component in diagnosing metabolic syndrome; thus, its notable reduction can lead to significant improvements in metabolic parameters with special emphasis on enhanced insulin sensitivity." (PMID 41374079, 2025). "PPAR-α agonists (known as fibrates) can ameliorate dyslipidemia while PPAR-γ agonists (glitazones) reduce insulin resistance, functioning as peripheral insulin sensitizers." (PMID 41471798, 2025). "For example, one study showed that supplementation with Bifidobacterium adolescentis improved visceral fat accumulation and increased insulin sensitivity in a model of metabolic syndrome." (PMID 39468772, 2025). "The hyper-HDL group showed significantly lower values for dyslipidemia prevalence, BMI, waist circumference, HbA1c, fasting insulin, LDL-C, LDL/HDL ratio, and TGs compared to other groups." (PMID 40089108, 2025). "These factors not only impact lipid profiles, but also disrupt insulin sensitivity, promote oxidative stress and induce inflammation, which are key processes that link dyslipidemia to cardiovascular and metabolic disorders." (PMID 40077646, 2025). "Pan-NR agonists, such as RGX-202, activate PPARα, PPARγ, and PPARδ, leading to improvements in lipid metabolism, insulin sensitivity, and fatty acid oxidation, with potential applications for metabolic syndrome, dyslipidemia, and CVD." (PMID 40926269, 2025). "Graphene-FIR therapy effectively mitigated body fat accumulation, improved dyslipidemia, and impaired liver function while enhancing insulin sensitivity." (PMID 40076847, 2025). "Supplementing with chromium has been shown to be effective in treating metabolic syndrome and insulin sensitivity." (PMID 39817379, 2025). "Levels of fetuin-B levels in patients with metabolic syndrome are by improvements in insulin sensitivity, with a positive correlation between fetuin B and oxidative stress." (PMID 41341131, 2025).
metabolic syndrome (continued). "Each index captures different IR-related dimensions (dyslipidemia, adiposity, insulin sensitivity), increasing the validity of findings and minimizing bias associated with reliance on a single marker." (PMID 40422582, 2025). "MASLD Liver Fat Score: This method uses metabolic syndrome parameters, fasting insulin, and liver enzymes to predict MASLD with high sensitivity and specificity." (PMID 40109726, 2025). "In the liver, this not only worsens steatosis but also promotes hepatic insulin resistance, gluconeogenesis, and dyslipidemia." (PMID 40869061, 2025). "Adherence to the DASH diet has been shown to improve metabolic disturbances in patients with type 2 diabetes and reduce sympathetic activity and improve blood pressure, lipids, and insulin sensitivity in individuals with metabolic syndrome." (PMID 40422864, 2025). "On the one hand, insulin prevents dyslipidemia by decreasing the release of free fatty acids (FFAs) from adipose tissue through inhibiting hormone‐sensitive lipase and the production of VLDLs." (PMID 41030912, 2025). "Micro-minerals such as phosphorus, potassium, and magnesium are complicated in diverse components of the metabolic syndrome, especially in the secretion of insulin." (PMID 40083990, 2025). "The most prevalent comorbidities were hypertension (82.5%) and dyslipidemia (63.1%), while the most commonly used medications were biguanides (86.5%) and insulin (43.4%)." (PMID 40869860, 2025). "If proven in future research, our contention would lend credence to a fructose restriction-focused intervention as a strategy to address IR, enhance insulin kinetics, and reduce dyslipidemia." (PMID 40429553, 2025). "Since TRF improved insulin sensitivity and reduced serum inflammation in normal-diet mice, we further explored its effects on metabolic syndrome in pathological states by using mice on a high-fat diet (HFD)." (PMID 39925816, 2025). "In patients with MASLD, LCDs demonstrate clinically meaningful improvements in insulin sensitivity, adiposity, and dyslipidemia, particularly when carbohydrate intake is restricted below 26% of total energy." (PMID 40933261, 2025). "These inflammatory mediators promote oxidative damage and impair insulin signaling throughout the body, which are fundamental characteristics of metabolic syndrome." (PMID 40861447, 2025). "Among them, eriodictyol can improve dyslipidemia, fatty liver and IR in diet-induced obese mice, promote insulin release through the cAMP/PKA pathway, which is related to the activation of GLP-1R." (PMID 40271065, 2025). "As noted, FMT from lean donors to individuals with metabolic syndrome significantly improved peripheral insulin sensitivity in a randomized controlled trial." (PMID 40871736, 2025). "It improves metabolic dysregulation in obese animals and humans by reducing insulin sensitivity and dyslipidemia." (PMID 40166691, 2025). "Visceral adiposity and metabolic dysfunction—insulin resistance, dyslipidemia, adipokine imbalance, and low-grade inflammation—establish a bidirectional liver–kidney crosstalk in MASLD." (PMID 41465744, 2025). "The review further addresses exercise-induced FoxO modulation in metabolic syndrome, insulin sensitivity, neurodegeneration, cardiovascular diseases, inflammation, and cancer, underlining the broad systemic impact of this signaling pathway." (PMID 40861274, 2025). "In both arms, participants with metabolic syndrome were older, with higher baseline systolic blood pressure, diastolic blood pressure, triglycerides, fasting blood glucose, fasting insulin level and insulin sensitivity assessed by HOMA‐IR." (PMID 39888728, 2025). "Metabolic syndrome, sometimes called syndrome X or insulin resistance syndrome, is deemed a critical health condition by the WHO marked by three key issues: excess belly fat, impaired insulin utilization, dyslipidemia, and hypertension." (PMID 41245414, 2025).
metabolic syndrome (continued). "These inflammatory mediators disrupt insulin signaling cascades, establishing a mechanistic link to the increased prevalence of metabolic syndrome (MetS) observed in males." (PMID 40429918, 2025). "Inflammation is a key precursor to metabolic syndrome, increasing risks of hypertension, visceral obesity, and dyslipidemia, which can damage pancreatic β-cells and reduce insulin secretion, contributing to T2D." (PMID 41255540, 2025). "Chronic exposure to a HFHF diet followed by streptozotocin administration is a well-established model for inducing insulin resistance, oxidative stress, and low-grade systemic inflammation, mimicking human metabolic syndrome conditions." (PMID 41179088, 2025). "Polyphenols and carotenoids have been suggested as alternative treatments for metabolic syndrome because they can improve insulin response, lower serum triglyceride concentrations, inhibit adipogenesis, and downregulate angiotensin-converting enzyme activity." (PMID 40143179, 2025). "In fact, high weight loss increases adiponectin levels and decreases proinflammatory cytokines, which leads to increased insulin sensitivity and decreased metabolic syndrome parameters." (PMID 40013194, 2025). "Numerous studies in adults, particularly among individuals who are overweight/obese or suffer from metabolic syndrome, have reported significant improvements in insulin sensitivity and lipid profiles following SIT." (PMID 41488919, 2025). "In conclusion, ROF helps improve IR in T2DM by reducing inflammation, lowering oxidative stress, boosting antioxidant levels, modulating dyslipidemia, and enhancing the expression of genes related to insulin signaling." (PMID 40689212, 2025). "Single‐dose oral FMT transplantation to patients with metabolic syndrome was safe and well tolerated and also improved insulin sensitivity." (PMID 40060755, 2025). "In insulin-resistant states, such as metabolic syndrome, hyperinsulinemia increases the protein expression of urate transporter 1 (URAT1) in the proximal tubules, leading to an enhanced uptake of UA." (PMID 39937787, 2025). "PPARα activation turned out to be a promising therapeutic method for treating dyslipidemia, inflammation, and insulin sensitivity." (PMID 39941353, 2025). "Recently, a cohort study from Pakistan and Cameroon showed that elevated body mass index (BMI), insulin, blood sugar, dyslipidemia, and hypertension were observed in an organophosphorus (OPs) insecticide exposure group." (PMID 40190760, 2025). "B-cell failure is primarily mediated by endoplasmic reticulum (ER) stress due to the metabolic syndrome’s increased insulin production." (PMID 39940428, 2025). "These inflammatory mediators disrupt insulin signaling pathways, exacerbate endothelial dysfunction, and contribute to hypertension, dyslipidemia, and hyperglycemia." (PMID 40217852, 2025). "Sex-specific hormonal and metabolic differences can significantly affect responses to interventions for metabolic syndrome, including changes in lipid metabolism, insulin sensitivity, and inflammatory pathways." (PMID 40565686, 2025). "In conclusion, among participants with metabolic syndrome, a small reduction in body weight and increased physical activity leads to enhancement of cortical GU measured under insulin clamp conditions." (PMID 40692323, 2025). "In recent years, the term “metabolic dyslipidemia” has been used to describe the type of dyslipidemia that results from the combined effect of insulin resistance and fat." (PMID 40108925, 2025). "R2 = 0.388), which included HbA1c, insulin, and diastolic BP, is closely aligned with the clinical definition of metabolic syndrome as outlined by IDF and NCEP ATP III criteria." (PMID 41002975, 2025). "This, in turn, results in a reversible decline in insulin sensitivity across multiple organs and cardiorespiratory endurance, accompanied by increased central and hepatic fat accumulation as well as dyslipidemia." (PMID 40329313, 2025).
metabolic syndrome (continued). "BCAAs and AAAs are known to impair insulin signaling and mitochondrial function when elevated, fostering an environment conducive to metabolic syndrome and T2D." (PMID 40575035, 2025). "Future research should explore the mechanisms linking RGS to insulin sensitivity and glucose metabolism, particularly in individuals with metabolic syndrome." (PMID 40352117, 2025). "Lastly, treatment modality (insulin vs. oral agents) and other comorbidities (hypertension, dyslipidemia, smoking) are potential confounders." (PMID 41159344, 2025). "Chronic hyperglycemia, insulin insensitivity, and dyslipidemia are the pathophysiology of this metabolic syndrome." (PMID 41030838, 2025). "Berberine, a plant alkaloid from Berberis vulgaris Rupr., is recognized for a bioactive improvement metabolic syndrome like insulin sensitive, and anti-inflammatory effect on gut microbiota." (PMID 40236479, 2025). "IR, a key feature of metabolic syndrome, reduces muscle cell sensitivity to insulin, impairing protein synthesis and promoting protein breakdown, leading to decreased muscle mass." (PMID 40373017, 2025). "These include a BMI of 44.68 kg/m2, “buffalo hump”, prediabetes (HbA1c 5.85%), insulin levels fourfold above normal, dyslipidemia, and elevated IGF-1 (646.7 ng/mL)." (PMID 40428329, 2025). "In a randomized trial, transferring stool from lean, healthy donors to males with metabolic syndrome produced a significant improvement in peripheral insulin sensitivity after 6 weeks." (PMID 40871736, 2025). "Results demonstrated that Car@PLGA-NPs, compared to free carvacrol, significantly improved insulin sensitivity, reduced fasting blood glucose, ameliorated dyslipidemia, attenuated inflammation, and mitigated oxidative stress in db/db mice." (PMID 41586316, 2025). "Bariatric surgery also improved blood glucose, insulin sensitivity, and dyslipidemia in MUO individuals." (PMID 41191655, 2025). "We demonstrated that these treatments can enhance insulin sensitivity and counteract the detrimental effects of ectopic fat deposition in the pancreas, which contributes to metabolic syndrome." (PMID 40260275, 2025). "Phytochemicals have emerged as promising therapeutic agents for modulating glucolipid metabolism and insulin sensitivity, demonstrating efficacy in preclinical models of metabolic syndrome." (PMID 40699849, 2025). "In parallel, the blood-based model featuring insulin, HbA1c, and diastolic BP best captures the key metabolic components typically seen in central obesity and metabolic syndrome." (PMID 41002975, 2025). "In the CNS, insulin plays significant roles in learning and memory, and AD patients have impaired insulin signaling that is identical to that noticed in metabolic syndrome." (PMID 40379890, 2025). "The naturally occurring histidine dipeptide l-carnosine also lowers MG levels in rodent models of metabolic syndrome and normalized insulin sensitivity, insulin secretion, and glucose tolerance in overweight and obese subjects." (PMID 40284990, 2025). "Hypoxia also promotes adipose tissue inflammation, which disrupts insulin signaling and contributes to the development of metabolic syndrome among COPD patients." (PMID 40070633, 2025). "Emerging evidence also suggests that the gut-derived hormone fibroblast growth factor 21 (FGF21), which is modulated by plant-based nutrient intake, plays a role in improving insulin sensitivity and energy expenditure in individuals with metabolic syndrome." (PMID 40871683, 2025). "Even short-term exposure to this form of nutritional stress is sufficient to activate the pathological features of metabolic syndrome such as impaired lipid metabolism in the liver and deregulated insulin and glucose metabolism." (PMID 40426854, 2025). "Clinical studies have shown that berberine can reduce blood glucose levels and enhance systemic insulin sensitivity in patients with metabolic syndrome." (PMID 40661082, 2025).